IFNG (interferon gamma)
Diseases named in the same sentence as IFNG in open-access papers (continued):
Sharing a sentence is not in itself a finding about the gene and the disease.
infection (continued). "In contrast to the identical number of ILC1s and NKs in the liver before infection, we observed that 48 h after infection, the number of ILC1s was decreased and ILC1s also showed impaired secretion of IFNγ, a cytokine that mainly functions during infection by intracellular bacteria." (PMID 30258450, 2018). "Effects of diet × infection (p = 0.004) modulated PBMC IFNG expression." (PMID 30778359, 2018). "Similarly, T cells with mutations in the Calcium channel ORAI1 activating protein Stim1 are unable to undergo apoptosis following infection leading to a significant increase in IFNγ in the lungs." (PMID 30258448, 2018). "Similarly, type 1 cytokines such as IFNγ and TNFα are generally present at similar levels in tissues after antibiotics treatment in uninfected mice but reduced at the site of infection in microbiota-depleted mice." (PMID 30429801, 2018). "Severe IV infection induces many cytokines; IFNαβ, TNFα, IFNγ, C-X-C motif chemokine (CXCL) 10 (CXCL10), CXCL9, C-C motif ligand (CCL) 2 (CCL2), CCL4, CCL5 and interleukin (IL)−6 (IL-6), IL-2, IL-8, and IL-10 have all be observed to be upregulated during severe IV infection in humans." (PMID 30250466, 2018). "Infection signaling, which involves elevated levels of interferon gamma (IFN-γ) and a release of copper into the plasma, may trigger activation of macrophages and increased import of copper, which enhances killing of phagocytosed bacteria." (PMID 30327441, 2018). "We then inhibited both IFNγ and Arg1 simultaneously during super-infection in WT and Stat2−/− mice." (PMID 30337919, 2018). "Moreover, there was an increase in the number of IFNγ-expressing CD8 Trm cells after the second infection in the pmif versus control RNA group when tested by ex vivo stimulation with sporozoites lysates." (PMID 30006528, 2018). "Moreover, HIV+ individuals in late stages of infection have lower numbers of HIV-specific T cell IFNγ producers compared to HIV-specific responses during early HIV infection." (PMID 29423061, 2018). "Likewise, IFNγ levels in G1 increased earlier than those in other intravenously infected groups, and IgG levels on day 21 post-infection (pi) were higher in G1 than those in other intravenously infected groups." (PMID 29739449, 2018). "We hypothesized that a differential effect of IFNγ on infected and bystander cells may explain the survival of C. trachomatis during a primary infection and its subsequent IFNγ-mediated clearance during a secondary infection." (PMID 29855501, 2018). "Notably, A20 deletion rendered intestinal organoids more susceptible to cell death and inhibition of barrier-related genes mediated by interferon-gamma (IFNγ), a cytokine also present at elevated levels during untreated infection." (PMID 29505600, 2018). "Observed discrepancies in the role of IFNγ during super-infection might be due to differences in the dose and the strain of bacteria." (PMID 30337919, 2018). "Similarly, OT-II cells expressing both TNFα and IFNγ significantly increased in LdWT (p = 0.0422) and LdCen−/− (p = 0.0448) infections upon blocking with α-CD200 antibodies." (PMID 29915577, 2018). "Each of these infections induces a strong pro-inflammatory response with high levels of IFNγ." (PMID 30467504, 2018). "Moreover, detection of IFNG produced by T cells is the most widely used method for monitoring immune responses following infection or vaccination." (PMID 29361774, 2018). "We also measured the levels of pro-inflammatory cytokines IFNγ, TNFα, IL-12, and IL-1β in cultured supernatant collected after 24, 48, and 72 h post infection to verify if the levels of these cytokines have any correlation with CD200 expression in parasite-infected DCs." (PMID 29915577, 2018).
infection (continued). "There is a credible immunological mechanism to explain this mutually exclusive phenomenon in that interferon gamma (IFN-γ) generated during infection down-regulates T-helper lymphocyte-2 (Th2) activity associated with the production of interleukin-4 (IL-4) which promotes IgE production." (PMID 29988421, 2018). "Furthermore, HIF1α acts a positive feedback mediator during this process and acts to sustain the role of IFNγ in macrophage activation, helping to control and restrain the infection." (PMID 30374347, 2018). "The mechanism by which Chlamydia creates a distinction in the effect of IFNγ on infected and bystander cells may be relevant for other nuclear proteins, such as NFκB, that are functionally disrupted during infection." (PMID 29855501, 2018). "These antigens includes ESAT-6 and its secretion partner CFP-10 and the fact that these antigens are recognized by the majority of infected individuals has enabled the development of the interferon gamma release assays (IGRA), an in-vitro diagnostic concept for specific detection of infection." (PMID 30157233, 2018). "Secondly, both IL-10 and IFNγ were more elevated during severe C0360/94 infection at 800 pg/ml and 1,200 pg/ml, respectively, compared to the 60 pg/ml and 250 pg/ml, respectively, during D83-144 infection." (PMID 29559699, 2018). "Interestingly, human Babesia WA1 parasites infection in mice resulted in upregulation of both TNFα and IFNγ resulting in severe pathogenesis and fatal disease." (PMID 29445365, 2018). "NK-originated IFNγ is critical in controlling Mycoplasma disease in early infection in mice." (PMID 29967623, 2018). "In contrast to the type I IFNs, IFNG was differentially expressed from 24 hpi in response to infection with both M. bovis strains and exhibited strain-specific differential expression at 24 hpi and 48 hpi, with greater expression in response to AF2122 infection than G18 infection." (PMID 29263113, 2018). "In addition, the higher SG287/91- and SGΔccmHidnTO-induced IFNγ transcription with regard to SP449/87 infection was statistically supported." (PMID 30028856, 2018). "Protection during secondary infection was conferred by IFNγ- and TNFα-producing γδ T cells." (PMID 30538697, 2018). "Moreover, a recent study shows a TLR9/IFNγ-dependent activation of autoreactive T-bet+CD11c+ atypical B cells in response to P. yoelii 17XNL infection in mice." (PMID 30387712, 2018). "GPT levels in CD4+IFNγ-/- T cell recipients including those that succumbed to the infection were generally normal, whether treated with isotype antibody or anti-TNFα, while serum GPT was enhanced in control animals compared to non-infected mice." (PMID 28222146, 2017). "Furthermore, CD4+IFNγ-/- T cells provided long-term control in those animals that survived the infection." (PMID 28222146, 2017). "All CD4+IFNγ-/- T cell recipients that received anti-IL-17A hardly lost weight upon R. typhi infection (left), showed a very weak temporary clinical score peaking on day 12 post infection (middle) and survived the infection (right)." (PMID 28222146, 2017). "CD4+ T cells express IFNγ in the infection of C57BL/6 as well as of BALB/c mice with R. typhi." (PMID 28770333, 2017). "Furthermore, in a M. ulcerans mouse footpad infection model it was found that IFNG knockout mice display a faster disease progression compared to wild type mice." (PMID 29046669, 2017). "Interestingly, when monocytes were exposed to IFNγ prior to infection, the percentage of parasitized cells dramatically increased to 60% at 12h and 80% at 24h of infection." (PMID 28892492, 2017). "CCR2 deficiency did not affect IFNγ production by NKT cells at 24 hours post-infection, but was associated with a significantly reduced percentage and total number of IFNγ+ γδ T cells." (PMID 28384349, 2017).
infection (continued). "We also considered the possibility that neutrophils themselves serve as a source of IFNγ during L. pneumophila infection, as neutrophils have been shown to produce IFNγ during T. gondii, Salmonella Typhimurium, Streptococcus pneumoniae, and other infections." (PMID 28384349, 2017). "When stimulated ex vivo with 1μM cognate TagV antigen, TCR-V cells primed by MuPyV.TagV(QN) infection yielded memory cells that were capable of co-producing IFNγ and TNFα to a significantly higher level than those recruited by MuPyV.TagV or MuPyV.TagV(AN) infection." (PMID 28410427, 2017). "However the greater effect of CD4+ T cell depletion than IFNγ neutralization on lung myeloid cell infection implied that target cell recognition was the key parameter, rather than susceptibility to IFNγ." (PMID 28394921, 2017). "IFNγ therapy has had some success in treatment of other infections in the context of ICL and so may have a future therapeutic role in the management of VL infection in patients with ICL." (PMID 28493863, 2017). "Infections were performed for 2 hours in cells pre-stimulated for 16 hours with IFNγ." (PMID 28945814, 2017). "Immune attack via IFNγ release leads to upregulation of PD-L1 creating an “immune shield” to protect normal mucosa from autoimmune attack in the setting of chronic inflammation or infection." (PMID 28938609, 2017). "In future, newer tuberculins more specific to infection with Mycobacterium tuberculosis, or a more practicable method of collecting blood specimens among children in field conditions for interferon-gamma release assays, may help overcome this problem." (PMID 28284250, 2017). "In summary, ethanol, infection, and surgery had significant impact on cellular differentiation of T helper cells of the Th1 sublineage, transcription levels of t-bet, and the released signature cytokine IFNγ in the lung." (PMID 29348965, 2017). "They suggest that during natural infection, lymphocyte-derived IFNγ may participate in the host defense strategy by up-regulating Hamp, which acts as an AMP to reduce iron in the alveolar space." (PMID 29089902, 2017). "Cellular source of interferon gamma during infection with African trypanosomes." (PMID 28936213, 2017). "Thus, we first examined the impact of neutrophil or Ly6Chi monocyte deficiency on IFNγ production by NK cells and focused on 24 hours post-infection, as the defect in IFNγ production was already evident at this timepoint." (PMID 28384349, 2017). "This likely reflects a difference in the timepoints analyzed in the two different studies, as we analyzed an earlier timepoint (day 1) post-infection, whereas they examined day 2 post-infection, which likely allowed for increased IFNγ production by these cells." (PMID 28384349, 2017). "Supporting this observation, cluster 3, which was enriched for Th1, NK, IL-12, and IFNγ pathways, was strongly associated with infection but not with TF or TP." (PMID 28966918, 2017). "Once the host cell was killed, Mtb was able to rapidly grow inside the dead infected macrophage regardless of whether the cells were monocyte derived macrophages (MDM) or alveolar macrophages, or whether the cells were exposed to IFNγ prior to infection." (PMID 28130921, 2017). "In addition, the authors showed that IL-18 was an important factor for immunity to C. parvum in Rag2−/− γc−/− mice and IL-18 promoted production of IFNγ by macrophages during infection." (PMID 28800747, 2017). "Intriguingly, our data suggest that neutrophils express high levels of Ifng mRNA, suggesting that neutrophils themselves may serve as a source of IFNγ, as has been observed in other infection models." (PMID 28384349, 2017). "Lymphokines such as interferon gamma (IFN-γ) and interleukin 4 (IL-4) stimulate B cells to produce antibodies and attract and activate immune cells such as macrophages and other lymphocytes at sites of infection (8, –, 11)." (PMID 28122790, 2017).
infection (continued). "Furthermore, CC16 modulates lung inflammatory responses to infection, injury, and allergen challenge by downregulating pro-inflammatory cytokines including IFNγ, IL-1, IL-6 and TNFα." (PMID 28380043, 2017). "Also, the roles of GC and endogenous Ifnγ were investigated and the implications of this study, in the context of immune consequences during infection-induced thymic atrophy, are discussed." (PMID 28091621, 2017). "All CD4+IFNγ-/- T cell recipients that finally succumbed to the infection continuously lost weight and developed a clinical score with similar kinetics or even a little earlier than control mice, whether treated with isotype or anti-TNFα antibody." (PMID 28222146, 2017). "Both Granzyme B and IFNγ expression peak on day 7 post infection in both strains of mice." (PMID 28770333, 2017). "Type I IFNs can work in concert with IFNγ to suppress erythropoiesis, and therefore it is possible that Type I IFNs may initiate the disruption of erythropoiesis earlier during infection." (PMID 28938907, 2017). "Autoantibodies, such as anti-IFNγ and anti-GM-CSF, are associated with infections in non-HIV patients with normal CD4 counts." (PMID 29333430, 2017). "However, if this miRNA is downregulated in the very early phase of infection this would also lead to an increased immune response as it was predicted to target viperine and interferon gamma." (PMID 28472924, 2017). "Because CB17 SCID mice develop severe liver necrosis upon R. typhi infection, we also assessed serum GPT levels as a measure for liver damage in all groups of mice at the time of death and in surviving CD4+IFNγ-/- T cell recipients at day 34 post infection when the experiment was terminated." (PMID 28222146, 2017). "Thus, during chronic infection phase, Brucella appears to be extremely well equipped to escape the IFNγ-mediated protective immune response and persist in the host." (PMID 28824630, 2017). "Early myeloid-driven activation of IFN-signalling may be beneficial for the host as evidenced by the finding that IFN I and IFNγ are both required for optimal immune cell recruitment during the initial pre-adaptive phase of Mtb-infection in a mouse model." (PMID 28863187, 2017). "In patients with anti-IFNγ autoantibodies who have severe disseminated infections with intracellular pathogens, especially non-tuberculous mycobacteria, rituximab has helped to reduce antibody levels allowing clearance of infection." (PMID 28848545, 2017). "Consequently, even if both NK cell-dependent and -independent IFNγ have a protective role in innate immunity against C. parvum infection, presence of NK cells significantly helps to contain infection." (PMID 29295550, 2017). "Additionally, inactivation of Cdu1 led to increased sensitivity of C. trachomatis for IFNγ and impaired infection in mice." (PMID 28347402, 2017). "Females also had increased expression of a number of IFNγ pathway related genes relative to males, suggesting that overexpression of this pathway in response to infection might contribute to more severe scarring." (PMID 28966918, 2017). "At the same time C3H/HeN mice show enhanced serum levels of IFNγ early in the infection with R. conorii which could be ascribed to NK cells." (PMID 28770333, 2017). "Highest levels of IFNγ were found at 48 hours after infection." (PMID 29348965, 2017). "We also measured cytokine production after C. albicans restimulation of splenocytes obtained from 2-DG or BPTES-treated mice after the infection, finding a significant reduction in the production capacity of IL-1β, IL-6, IL-10, TNFα and IFNγ in mice treated with 2-DG." (PMID 28922415, 2017). "Bacterial numbers in the organs even of those CD4+IFNγ-/- T cell recipients that succumbed to the infection were clearly reduced at the time of death compared to R. typhi-infected control mice, demonstrating bactericidal activity of CD4+IFNγ-/- T cells in vivo." (PMID 28222146, 2017).
infection (continued). "Following infection with Lm, innate immune responses are rapidly triggered in a stepwise manner, with the hallmarks of early resistance to infection being the production of interferon-gamma (IFN-γ) by natural killer cells and the subsequent activation of macrophages." (PMID 28588899, 2017). "Because IFNγ/IL10 CD4 T-cell responses have been associated with high antigen burden in other systems, we assessed the relationship of Pf–specific responses and parasite density during the most recent infection (within 3 months prior to blood draw)." (PMID 29097996, 2017). "Natural killer cells are also significant producers of inflammatory cytokines during early infection, prior to the priming, clonal expansion and activation of antigen-specific T cells; in particular, NK cells are an important source of interferon gamma (IFN-γ)." (PMID 28337195, 2017). "The intravacuolar bacteria Chlamydia trachomatis and Salmonella typhimurium are likewise targeted by IFNγ‐driven host responses in the acute stages of infection, resulting in C. trachomatis reticulate bodies forming an aberrant non‐dividing form, and in S. typhimurium clearance." (PMID 26874079, 2016). "Further support for this hypothesis came from our histopathological analysis, where a trend to lower levels of extracellular acid-fast debris was found in the IFNγ-/- mice at the early intracellular stages of the infection." (PMID 26863011, 2016). "T cell-independent cNK-produced IFNγ is critical for early control of infection." (PMID 27721814, 2016). "Hence, MC play a major role in clearance of L. pneumophila and are an important source of IL12, which is largely responsible for inducing IFNγ after infection." (PMID 27300652, 2016). "With other Th1 type cytokines IL-1, IL-12 and IFNγ it contributes to the control of the infection." (PMID 27168977, 2016). "The decrease in intracellular IFNγ production by CD3+ lymphocytes in this infection model could be related to impaired activation of CXCR6+ iNKT cells since Salmonella typhimurium glycolipids are known to stimulate iNKT cell responses." (PMID 27471636, 2016). "The frequency of IFNγ+ cNK cells in PEC increased after infections with all three strains." (PMID 27721814, 2016). "IFNG protein has previously been shown to be produced by human monocyte-derived Mø and DC in response to S. Typhimurium infection, albeit at a later time-point of infection." (PMID 27000047, 2016). "As hypothesized, the levels of inflammatory mediators (IL-6, CCL2, CCL3, CXCL1, CXCL10 and IFNα as expected) were lower in the blood and the spleen of Ifnar1-/- mice compared to WT counterparts at all times post-infection, except for IFNγ." (PMID 27792766, 2016). "However, IFNγ-producing CD4+ cells most likely act in the later stages of primary infection, during the adaptive phase of the response, since death in CD4-deficient neonates is delayed until ≥15 days post infection." (PMID 28119902, 2016). "Following restimulation at 7 days post-infection, a similar percentage of aPKC-deficient CD8+ T lymphocytes produced IFNγ and TNFα compared to wild-type control cells; however, the percentage of aPKC-deficient cells that were capable of producing IL-2 was reduced." (PMID 26765121, 2016). "A more recent test for infection is the interferon gamma (IFN-γ) release assay (IGRA), in which blood is stimulated with two M. tuberculosis-specific antigens and then assayed for IFN-γ by enzyme-linked immunosorbent assay or enzyme-linked immunosorbent spot assay." (PMID 27048801, 2016). "As compared to CD4-Cre-IL-10flox/flox (Cre-) control mice, Cre+ mice mounted elevated CD4+/IFNγ+ responses in the salivary glands to multiple MCMV antigens throughout the course of infection, most notably M25- and m142-specific cells at d14 pi when peak IL-10+ responses were observed in Cre- mice." (PMID 27926930, 2016).